CD47 (CD47 molecule)
Diseases named in the same sentence as CD47 in open-access papers (continued):
Sharing a sentence is not in itself a finding about the gene and the disease.
cancer (continued). "CD47 mAbs inhibit the interaction between CD47 and SIRPα and thereby activate TAM to phagocytose cancer cells." (PMID 36961012, 2023). "The results showed that the mRNA expression of CD24, CD47, and CD155 was presented in these four cancer types, which was consistent with TCGA results." (PMID 38016957, 2023). "Phagocytosis checkpoints, such as CD47, CD24, MHC-I, PD-L1, STC-1 and GD2, have emerged as essential checkpoints for cancer immunotherapy by functioning as “don’t eat me” signals or interacting with “eat me” signals to suppress immune responses." (PMID 36882399, 2023). "Even when cancer cells were resistant to anti-HER2 trastuzumab, anti-CD47 (magrolimab) combined with trastuzumab dramatically reduced HER2+ breast cancer with heightened efficacy." (PMID 38035101, 2023). "However, the underlying mechanism maintaining CD47 protein stability in cancer is not clear." (PMID 36823443, 2023). "Below, we summarize outstanding questions that must be addressed for CD47-targeted therapy to become the next successful IO for NSCLC and other cancers." (PMID 37958404, 2023). "By enhancing our understanding CD47’s role in the TME, further research can optimize the design and delivery of CD47-targeted therapies for cancer patients, ultimately improving treatment outcomes." (PMID 38188674, 2023). "The CD47/SIRP-α axis is a well-established innate immune checkpoint, in which overexpression of CD47 on cancer cells triggers SIRP-α-mediated inhibition of cancer cell phagocytosis." (PMID 38116002, 2023). "However, CD47 could play a different role among different cancers." (PMID 35697717, 2022). "However, hypoxia may have beneficial effects on cancer therapy via SIRPα-CD47 axis." (PMID 36071472, 2022). "To further explore the role of CD47, HSPA5, HYOU1, and PDIA4 genes in cancer, we used the human protein atlas (HPA) database to analyze the expression of these target genes in cancer and their impact on the ability of cells to survive." (PMID 35678681, 2022). "While CD47 and STAT3 showed strong heterogeneity in late-stagecolorectal cancer, TAGL was highly expressed in the early- and late-stagecolorectal cancers." (PMID 35605973, 2022). "We used reference anti-CD47 mAb clone Hu5F9-G4 (or Hu5F9) to compare the binding of STI-6643 on two human and two canine cancer cell lines." (PMID 35664753, 2022). "This concept was further supported by the positive correlation of CEP192 with characteristic onco-fetal genes, also known as cancer stem cell markers, including CD24, SOX9, CD47, and POU5F1 (OCT4)." (PMID 36238304, 2022). "For example, some SIRPα-CD47 targeted clinical trials have entered phase III and manifested great effects in the treatment of cancer patients." (PMID 36497444, 2022). "Cancer cells were reported to take advantage of ICMs, such as PDL1 and CD47, to achieve immune evasion." (PMID 35152264, 2022). "An Anti-PD-L1 (A12) CAR-T with the ability to secrete anti-CD47 VHH (variable heavy domain of heavy chain antibodies or nanobodies) (A4), developed by Xie, represented a novel strategy for cancer treatment." (PMID 35418166, 2022). "CD47-functionalized MSC EVs carrying KRASG12D siRNA are a promising vehicle for reducing KRAS expression in patient-derived xenograft mice, resulting in cancer cell apoptosis, inhibition of metastasis, and increased overall survival without cytotoxic effect." (PMID 36297672, 2022). "In this context, we demonstrated for the first time that CD47 is highly expressed in UTUC at mRNA and protein level, providing a theoretical basis for the following cancer-specific targeted imaging." (PMID 35295998, 2022).
cancer (continued). "Since DSP107 potently triggered 4-1BB costimulatory signaling, its effect on T cell-mediated killing of cancer cells was assessed by co-culture of isolated CD3+, CD4+, or CD8+ T cells with the CD47-positive NHL line SC-1.scFvCD3." (PMID 35287686, 2022). "In summary, this study combined VCMMAE with anti-CD47 mAbs, emphasizing a novel and promising immunotherapy method for direct killing of NSCLC, which provides a valuable new way to meet the needs of the cancer therapy field." (PMID 35646646, 2022). "Treatment with CD24 mAb was superior to CD47 mAb in MCL and was comparable in magnitude to the effect observed in carcinoma lines." (PMID 35625912, 2022). "Taken together, CD47 gene expressions are regulated by multiple transcription factors, which could be transcriptional modification by pyroglutamate formation that enhances the binding of CD47 to SIRPα, consequently, inhibits phagocytosis by phagocytes and promotes cancer cell immune escape." (PMID 34512146, 2021). "On the other hand, our results show that exposure of cancer cells to relatively high levels of CXCL12 induces the UPR and calreticulin release, which together with CD47 internalization contribute to cell phagocytosis by macrophages." (PMID 34561422, 2021). "Some of the APA targets are surface receptors with well-known involvement in cancers (CD44, CD47, and CD59)." (PMID 34521731, 2021). "There are several other examples for the ectopic expression of immune cell genes in cancer, such as CD36, CD70, CD40, CD47, CD172 and IDO1." (PMID 34885093, 2021). "Optimize physicochemical properties (size, shape, charge); Surface modification: PEGylation; Self‐peptide (CD47) functionalization; Biomimetic membrane coating (e.g., RBC, leukocytes, platelets, macrophage, cancer cells)." (PMID 33977060, 2021). "As the first-in-class anti-CD47/CD19 bsAb, TG-1801 is a fully humanized IgG1, targeting the ‘don’t eat me’ self-defense signal which defends cancer cells against the immune system." (PMID 34305918, 2021). "The result showed TAMs would receive activated signals from cancer cells through GAS6-AXL, RPS19-C5AR1, FAM3C-LAMP1, CD47-SIRPA, and VEGFA-NRP1/NRP2 L–R pairs in TME." (PMID 34676217, 2021). "Although SLFN11 knockdown does not protect CD47-null PC3 cells from the effect of ionizing radiation as in other cancer cells, the low SLFN11 in CD47-null PC3 cells reduces the sensitivity of these cells to DNA damaging agents such as etoposide." (PMID 34571887, 2021). "The bispecific antibody dual targeting CD47 and TIGIT has also been designed for cancer immunotherapy (WO2020259535)." (PMID 34068552, 2021). "Collectively, consistent with the previous literature, our results revealed the over-expression of CD47 and PVR in tumors, suggesting the promising role of CD47 and PVR in cancer immunotherapy." (PMID 34068552, 2021). "CD47–SIRPA axis-targeting agents can induce the phagocytosis of cancer cells by macrophages, which results in growth inhibition and regression of cancers in experimental conditions." (PMID 33799989, 2021). "Both embryo JEG-3 and cancer MCF-7 cells expressed high sLex, CD47, CAMs, while both endometrial RL95-2 and endothelial HUVECs exhibited high integrins and ICAM-1." (PMID 34556175, 2021). "In contrast to PD-L1 and CD47 expression, the induction of EGFR on the cancer cells was significantly increased when cultured with high-density MSCs but was unchanged by the incorporation of the innate immune cell compartment." (PMID 34885111, 2021). "The functions of TNFα include regulating the EMT transition in many cancers, These pathways are interrelated and are elevated via subsets of MHC-I+ EVs in a CD47-dependent manner." (PMID 34829933, 2021). "Compared to treatment with IgG control antibody, a monoclonal antibody against CD47, B6H12, enhanced the in vitro phagocytotic activity of human macrophages against cancer cells and prolonged the survival of mice with intraperitoneal metastatic cancer." (PMID 32082311, 2020).
cancer (continued). "The interaction between CD47 and ENO1was further confirmed by co-IP assay in HEK293 cells as well as SW480 cancer cells." (PMID 32226539, 2020). "Data presented in an abstract showed it selectively blocks CD47- SIRP α, promoting phagocytosis of cancer cells and sparing T-cells and RBCs in vitro." (PMID 32677994, 2020). "Among cancer cells, HCT116 and SW480 had a relatively higher level of CD47, while HCT8 and DLD1 cells exhibited a lower level of CD47." (PMID 32226539, 2020). "Among pediatric cancers, we find the highest expression of CD47 in M7 AML and ALL, nearly as high as the highest adult cancers." (PMID 35582455, 2020). "Several different types of anti-CD47 antibodies such as MIAP301, MIAP410, Hu5F9-G4, CC-90002, SRF231, B6H12.2, ALX148 has been use in during cancer and infection." (PMID 32882841, 2020). "A positive correlation between CD47 and SLFN11 was also found for the cell lines in the Cancer Cell Line Encyclopedia (Spearman's correlation 0.193, p = 1.6 × 10−9, q = 2.6 × 10−8)." (PMID 31632920, 2019). "Like other cancer cell lines, MDA-231 cells are known to express CD4735 and thus target cells were treated with an anti-CD47 antibody to assess antibody-dependent phagocytosis." (PMID 30760760, 2019). "An initial survey of TCGA cancer datasets with sufficient RNAseq data indicated that the positive correlation between CD47 and SLFN11 mRNA expression observed in Jurkat T cells extends to a subset of human cancers." (PMID 31632920, 2019). "Our PC3 cell data indicates that CD47 regulation of SLFN11 and responses to stress is more restricted in this cancer cell line." (PMID 31632920, 2019). "CD47 blockade is, therefore, a novel validated target for macrophage-mediated ICB-based cancer immunotherapy." (PMID 31540045, 2019). "This was further corroborated by a decrease in the mRNA expression of various AML stem cell makers like (CD47, CD34 and CD126) upon treatment of these cancer cells with triptolide for 24 h." (PMID 31109340, 2019). "CD47 is a promising new target in cancer immunotherapy and recently the pro-phagocytic signal SLAMF7 has been shown to have a crucial role in phagocytosis induced by CD47-blocking antibody in hematological tumors." (PMID 30710089, 2019). "Mouse cancer cells −4T1, LCC, B16F10 and CT26- had CD47+ cells with high expression rates of 99.5%, 99.4%, 99.6%, 99.8%, respectively, in comparison with the isotype control." (PMID 30872703, 2019). "Our data demonstrated that the synergy anti-CD47 and anti-CD274 showed the least number of tumorigenesis, and the inhibition cancer metastasis effect was more obvious than antibody alone." (PMID 30872703, 2019). "It has been shown in some cancer cell lines that suppression of MYC with BET inhibitors such as JQ1 reduced programmed cell death ligand 1 (PD-L1) and CD47 expression." (PMID 31288832, 2019). "There results validated that CD47 and CD274 were highly expressed in a series of mouse cancer cells." (PMID 30872703, 2019). "MYC upregulates the expression of immune checkpoints CD47 and PDCD1L1 on cancer cells by direct interaction with promoters of these two genes." (PMID 31824865, 2019). "Further studies will be required to define the relative importance of these two mechanisms in the cross talk between CD47 and SLFN11 in each cancer type." (PMID 31632920, 2019). "Since the discovery of CD47 as a therapeutic target in AML, subsequent studies have validated the role of CD47 across multiple cancer types." (PMID 32038992, 2019). "In multiple types of cancer, silencing of MYC leads to a significant reduction in the transcription and expression of CD47 and PDCD1L1, both in vitro and in vivo." (PMID 31824865, 2019). "CD47-mediated triggering of SIRP-α inhibits phagocytic removal of cancer cells and reduces the immunogenic processing of cancer cells by macrophages and dendritic cells." (PMID 30710089, 2019).
cancer (continued). "Several studies have reported the aberrant expression of multiple antigens by cancer stem cells in AML, including CLL-1, CD47, CD44, and ALDH." (PMID 29799854, 2018). "Since MYC is upregulated in MM and, among others, enhances PD-L1 and CD47 membrane translocation in cancer cells, it is possible that MYC also regulates PD-L1 and CD47 expression in MM cells." (PMID 29783691, 2018). "In conclusion, one of these CD cell surface markers, CD47, CD44, or CD24, can be an attractive new target for the elimination of CSCs by CART cells in multiple cancer types." (PMID 28290053, 2018). "The CD47-CAR-T cells produced Il-2 cytokine against cancer cells that was significantly higher in SKOV3 cells, highly positive for CD47 than in A549 and Hep3B cells with lower expression of CD47." (PMID 29065481, 2017). "It demonstrates the high efficacy of CD47-CAR-T cells against cancer cells in vitro and in vivo and provides a novel anti-cancer cellular therapeutics." (PMID 29065481, 2017). "In fact we showed that ovarian SKOV-3 cancer spheres express a high level of CD47 tumor antigen, and future study will elucidate the mechanisms of CD47-ACR-T cells against CD47-positive cancer stem cells." (PMID 29065481, 2017). "The CD47-CAR-T cells effectively killed high-expressing cancer cell lines such as A1847, SKOV-3, and CAR-T cells killed much less A549 and Hep3B and cells with a lower level of CD47 versus T cells or Mock-CAR-T cells." (PMID 29065481, 2017). "We engineered humanized CD47-CAR-T cells and demonstrated that it also effectively and specifically killed CD47-positive cancer cells." (PMID 29065481, 2017). "Using fluorophore-conjugated antibodies, we set out to measure expression levels of the exosomal surface marker CD63 and other cancer-related proteins shown in our mass spectrometry analyses of exosomes, such as CD44 and CD47." (PMID 27819324, 2016). "We then optimized the detection procedure to measure CD47 and CD44 levels in the circulating exosomes from human blood (cancer patients n = 60 and healthy controls n = 60)." (PMID 27819324, 2016). "The analyses revealed that all cancer cell lines, except SPCA-1, expressed significantly higher levels of CD47 protein and mRNA than 16HBE cells." (PMID 27411490, 2016). "In the simulations, we focused only on CD44, CD47 and MET overexpressions and underexpressions (excluding EPCAM) because we are considering the cancer cells that are already in the blood vessels." (PMID 25978366, 2015). "MT1A2 mousemammary cancer cells were implanted in the mammary fat pads of FVB mice and IgG controlor anti-CD47 antibody treatment commenced upon detection of palpable tumors." (PMID 25621565, 2015). "CRT expressed on the cell surface is considered as an “eat-me” signal for multiple human cancers, and this prophagocytic function of CRT is disrupted by an antiphagocytic signal CD47." (PMID 25918716, 2015). "Nevertheless, some putative side-effects of using TAX2 as an anti-cancer agent still need to be explored, particularly as TSP-1 interaction with CD47 and/or CD36 is also known to modulate platelet aggregation." (PMID 26578962, 2015). "Similar to CD47, CD200 is overexpressed in many cancers as a mechanism to avoid immunosurveillance detection by CD200R-containing leukocytes." (PMID 25705515, 2014). "A population of CTCs from patients with primary luminal cancer (expressing EPCAM, CD44, CD47 and MET) generated multi-site metastases when injected into mice." (PMID 24286369, 2013). "CD166 has also been suggested to play a critical role in various human cancers and as a potential therapeutic target for cancer initiating cells, similar to CD44 and CD47." (PMID 22880034, 2012). "CD47/IAP is also shown to be necessary for the electrophysiological response of mouse lung fibroblasts and OV10 carcinoma cells to mechanical stimulation." (PMID 18186923, 2008).
cancer (continued). "PSFL‐NK13, while lacking hemolytic properties, disrupts CD47/αvβ3 interactions on cancer cell membranes without affecting erythrocytes." (PMID 41168993, 2026). "Here, a CD47–SIRPα immune checkpoint treatment is investigated that mitigates anemic side effects by selectively interfering with the costabilization of CD47 and integrin αvβ3 on cancer cell surfaces, a phenomenon absent in erythrocytes." (PMID 41168993, 2026). "Functional studies indicated that CD47 does not regulate cell proliferation in NSCLC cells like it does in other cancer types." (PMID 42007973, 2026). "Currently, several CD47-targeting antibodies, either alone or in combination with chimeric antigen receptor (CAR) T cells, are being tested in clinical trials, with varying degrees of success depending on the cancer type." (PMID 39967663, 2025). "This suggests that MCS selectively influences cancer cells expressing high levels of CALR without affecting the self-nonself recognition system mediated by SIRPα-CD47 and LRP-CALR interaction in macrophages." (PMID 39744689, 2025). "We find that cancer cells release blebbisomes containing an abundance of immune evasion and inhibitory immune checkpoint proteins, including PD-L1, PD-L2, B7-H3, VISTA, PVR, Nectin-2, HLA-E, CD73 and CD47." (PMID 39984653, 2025). "In this study, we generated Hu1C8, a humanized anti-CD47 monoclonal antibody that demonstrated increased selectivity for binding to CD47 on cancer cells and lacked hemagglutination activity." (PMID 40578556, 2025). "Cancer cells express CD47, a "do not eat me" signal, which interacts with signal regulatory protein alpha (SIRPα) on macrophages to prevent phagocytosis." (PMID 40528159, 2025). "Cancer cells frequently express do-not-eat-me signals such as CD47, which binds to the inhibitory receptor SIRPα on macrophages, effectively blocking macrophage-mediated phagocytosis." (PMID 41243973, 2025). "However, CD47, ubiquitously expressed in normal tissue, is highly expressed by a wide range of cancer cells and blocks the phagocytosis of CRT-expressing cancer cells." (PMID 39858072, 2025). "Therefore, understanding and modulating phagocytic pathways, including the CD47-SIRPα axis and TAM behavior, holds significant potential for improving cancer immunotherapy outcomes." (PMID 40396172, 2025). "Finally, there is evidence in the literature that the CD47/TSP-1 pathway has diverse effects on the immune system and represents a novel target for potential cancer therapeutics." (PMID 38638433, 2024). "Using MuSyC analysis, we found that synergy could occur with respect to maximal efficacy, potency, and/or cooperativity for the combination of an anti-CD47 antibody with EGFR TKIs, lorlatinib, or sotorasib when used with their respective cancers." (PMID 38483480, 2024). "However, the authors selected various cancer cell lines (including Raji, Daudi, NCI-H929, L-1236, Reh and MOLM-13) due to the expression profile of CD38 and CD47 making them the suitable candidates for study." (PMID 38983860, 2024). "Therefore, CD47-CAR-macrophages hinder the CD47/SIRPα axis and also self-activate to launch an assault the CD47-positive cancer cells." (PMID 39411712, 2024). "Single-cell RNA-seq analysis of a primary BC sample, focusing on examining the expression patterns of CD47, CD24, CD274, SIRPα and Siglec-10 at the individual cell level, revealed a prominent expression of CD47 and CD24 in cancer cells, notably higher than that of CD274." (PMID 38971872, 2024). "IMM0306 activates macrophages and NK cells by blocking the connection between CD47 and SIRPα and engaging FcγR, resulting in excellent cancer-killing effectiveness without binding activity on human RBCs and no hemolytic side effects." (PMID 39040441, 2024). "It demonstrated the high potency of CD47-CAR-T cells against cancer cells in vitro and provided a novel anticancer cell therapy." (PMID 38832992, 2024).